MTOR (mechanistic target of rapamycin kinase)
Diseases named in the same sentence as MTOR in open-access papers (continued):
Sharing a sentence is not in itself a finding about the gene and the disease.
neurodegenerative disease (continued). "Here, mTOR is a common target of miR-99 and miR-100, and it is also a pivotal molecule involved in neurodegenerative diseases." (PMID 26635599, 2015). "mTOR plays critical roles in cellular processes related to cell growth, metabolism, tumorigenesis, neurodegenerative diseases, cellular senescence, organismal aging and age-related diseases." (PMID 26600389, 2015). "Among the numerous components involved in the regulation of autophagy and neurodegenerative diseases, mTOR signaling is a key component that coordinately regulates the balance between neurodegeneration and autophagy in response to stress." (PMID 25393306, 2014). "YY1 is a ubiquitous transcription factor previously noted to regulate several genes associated with neurodegenerative diseases including BACE1 and APP, SNCA, EAAT2, MTOR and PPARGC1A." (PMID 25187168, 2014). "A challenge for the development of treatments of neurodegenerative diseases based on mTOR inhibition is that mTOR is part of a central signaling system regulating many cellular functions." (PMID 24307901, 2013). "Our findings show that CysC plays a protective role under conditions of neuronal challenge by inducing autophagy via mTOR inhibition and are consistent with CysC being neuroprotective in neurodegenerative diseases." (PMID 20352108, 2010). "Since mTOR is associated with muscular growth, a dysregulated mTOR function may play a role in the pathophysiology of ALS and possibly other neurodegenerative diseases." (PMID 40299664, 2025). "It was shown that enhanced autophagy was associated with extended lifespan in model organisms (such as worm and mouse), and increasing evidences indicated that several genes (including LAMTOR4, LAMTOR2 and NPRL3) involved in mTOR network regulated autophagy and neurodegenerative diseases." (PMID 37582720, 2023). "The hyperactivation of the mTOR signaling pathway leads to severely impaired autophagy, which results in the accumulation of abnormal proteins in neurons, which is a major feature of neurodegenerative diseases." (PMID 37238743, 2023). "Antioxidants could be administered to prevent Cd-induced neurodegenerative diseases, since redox-based signalling mechanisms coordinate the mTOR complexes." (PMID 36834835, 2023). "Abnormal levels of mTOR, particularly mTORC1, can lead to excessive mitophagy, and the inhibition of mTOR appears to be a novel approach to promoting mitophagy, possibly improving the symptoms of neurodegenerative diseases." (PMID 36267702, 2022). "Numerous studies have revealed that dysfunction of mTOR signaling in the brain may be deeply correlated with cognitive dysfunction in DM and neurodegenerative diseases." (PMID 34784444, 2022). "While the crosstalk between mTOR and Nrf2 in neurodegenerative diseases could provide novel therapeutic treatments, there are limited studies that have investigated the mechanism." (PMID 35805130, 2022). "Additionally, high expression of mTOR-inhibiting autophagy has been demonstrated in neurodegenerative diseases." (PMID 36704351, 2022). "Furthermore, elevated phosphorylated mTOR and its downstream protein targets have been observed in AD pathology suggesting the implication of mTOR in neurodegenerative diseases." (PMID 35805130, 2022). "Moreover, excess PARP1 activation was demonstrated in aging and neurodegenerative diseases resulting mitochondrial dysfunction, neuroinflammation and dysregulation of autophagy (and mitophagy; e.g., via mTOR activation)." (PMID 34206738, 2021). "Moreover the mTOR/AKT/S6K1 pathway is also extensively involved in neurodegenerative diseases, including ALS, through apoptosis/survival pathway regulation." (PMID 32493926, 2020).
neurodegenerative disease (continued). "Therefore, studies that elucidate the role of the Rheb–mTOR signaling pathway in neurodegenerative diseases are of great importance." (PMID 32188096, 2020). "However, recent experimental evidences suggest that new autophagy enhancers can act through both the MTOR-dependent and the MTOR-independent pathways, representing potential therapeutic agents for the treatment of neurodegenerative diseases." (PMID 31412596, 2019). "Whether mTOR inhibits ULK in neurons during development or neurodegenerative disease remains controversial." (PMID 31676756, 2019). "We propose that such alterations may be due to activation of mTOR signaling, which is considered a contributor to the progression of AD and of other neurodegenerative diseases." (PMID 31208023, 2019). "Due to opposite roles of the mTOR pathway in neurons being still largely unknown, the detailed mechanisms of autophagy on neurodegenerative diseases are still in need of further study." (PMID 29382106, 2018). "Moreover, herbal compounds show opposite impact on the mTOR pathway for neuroprotection in neurodegenerative disease models." (PMID 29382106, 2018). "Rapamycin and other mTOR inhibitors increase the clearance of abnormal protein aggregates and slow neurodegeneration in both cell and animal models of a variety of neurodegenerative diseases, including AD, PD, spinocerebellar ataxia type 3, and frontotemporal dementia." (PMID 28293421, 2017). "Treatment with Rp and related mTOR inhibitors could be beneficial in slowing down and controlling progression of neurodegenerative diseases." (PMID 28335215, 2016). "The autophagy activator, rapamycin, which is an antifungal and immunosuppressant compound that targeting in inhibition of the mTOR signal, has been identified its potential therapeutic effect on numerous neurodegenerative diseases including TDP-43-related pathogenesis." (PMID 27769241, 2016). "RTP801 progressive elevation and its inhibitory function towards pro-survival kinases mTOR and Akt could explain its role in several neurodegenerative diseases." (PMID 25324725, 2014). "mTOR signaling is inhibitory of autophagy, plays a crucial role in cellular proliferation and migration (functions important in cellular repair), contributes to cerebrovascular dysfunction, and plays a role in many neurodegenerative diseases, including dementia." (PMID 41310161, 2025). "In addition, targeting the mTOR signaling pathway may offer a therapeutic angle for neurodegenerative diseases since mTOR inhibition has been shown to induce pexophagy." (PMID 40002313, 2025). "While senescent astrocytes exhibit proinflammatory profiles partly driven by active mTOR signaling and DNA-damage response pathways, these findings highlight the shifting roles of mTOR in aging astrocytes and its potential as a therapeutic target in neurodegenerative diseases." (PMID 40065324, 2025). "In this review, we discuss mTOR and Nrf2 complexes, their crosstalk, and roles in neurogenesis, and the implication in neurodegenerative diseases such as AD, PD, and HD, and how a better understanding of those complexes could provide possible answers to questions mentioned previously." (PMID 35805130, 2022). "Moreover, rapamycin, an mTOR inhibitor, has been shown to effectively reduce abnormal Aβ and tau protein deposition and improve learning and memory abilities by promoting autophagic flux in neurodegenerative diseases." (PMID 34784444, 2022). "Additionally, chronic activation of mTOR is observed in neurodegenerative diseases." (PMID 36206843, 2022). "Thus, developing mTOR-independent inducers of autophagy could be a promising therapeutic strategy for neurodegenerative diseases." (PMID 34925009, 2021). "Therefore, inhibiting the PI3K/mTOR/GSK3β pathway may be an effective treatment for neurodegenerative diseases." (PMID 32832542, 2020).
neurodegenerative disease (continued). "mTOR signalling responds and integrates signals from nutrients, growth factors, energy and stress, and regulates cellular proteostasis, thus contributing to age-related neurodegenerative diseases, making it an attractive target for further investigation in ALS pathogenesis." (PMID 30635270, 2019). "Hence, lithium might be considered as a treatment strategy to enhance autophagy in an mTOR-independent manner in neurodegenerative diseases such as HD." (PMID 31191249, 2019). "Emerging strands of evidence indicate that the disruption in the mammalian target of rapamycin (mTOR) signaling pathway impacts multiple cellular functions, including autophagy, glucose metabolism, cell growth, and mitochondrial functions, that are central in aging and neurodegenerative diseases." (PMID 31998117, 2019). "Therefore, this study provides new evidence of the detrimental role of mTOR in neurodegeneration, which might represent an important target for the treatment of neurodegenerative diseases." (PMID 28143498, 2017). "Since the mTOR complexes are believed to be regulated by redox-based signalling mechanisms, it has been hypothesised that antioxidants may be exploited for the prevention of cadmium induced neurodegenerative diseases." (PMID 28353644, 2017). "Thus, the efficacy of mTOR inhibitors in clearing a variety of neurodegenerative disease proteins may be due to the ability of these drugs to upregulate both the proteasomal and autophagic routes of protein degradation." (PMID 28293421, 2017). "Interestingly, since RTP801 is able to inactivate protein translation, via mTOR, and survival, via Akt, its pro-apoptotic role may be relevant to other neurodegenerative diseases." (PMID 25324725, 2014). "An imbalance between them can lead to neurodegenerative diseases like ALS, which are characterized by altered levels and activation in mTOR." (PMID 40299664, 2025). "Studies aimed at reducing the detrimental effects of mTOR inhibition in ALS and other neurodegenerative diseases require a thorough investigation of its mechanisms and the metabolic pathways involved in its signaling." (PMID 40299664, 2025). "Seven genes were observed to be involved in both infections of three coronaviruses and two neurodegenerative diseases, including the HSP90AA1, ALDH2, CAV1, COMT, MTOR, IGF2R and HSPA1A." (PMID 37015947, 2023). "In neurodegenerative diseases, autophagy has been reported to be stimulated in response to AMPK/mTOR pathway activation." (PMID 37630980, 2023). "We tested known mTOR-dependent and -independent autophagy compounds used previously in models of SCA3 and related neurodegenerative diseases." (PMID 36980234, 2023). "Rapamycin, a selective inhibitor of the mammalian target of rapamycin (mTOR), has been reported to be beneficial in TDP-43-related neurodegenerative diseases, such as FTLD-U." (PMID 36614118, 2022). "Therefore, it will be interesting to see how the two forms of CDC42 affect the expression and/or activation levels of mTOR and the EGFR in adult brains and whether the deregulation of these CDC42 splice variants is involved in the pathogenesis responsible for neurodegenerative diseases." (PMID 36206843, 2022). "In neurodegenerative diseases, such as AD, p-AKT and p-mTOR are activated by Aβ and impair autophagy induction." (PMID 32514180, 2020). "The autophagic process was altered in neurodegenerative diseases and modulated by PI3K/Akt/mTOR activity, while the interplay between them was complicated." (PMID 31658620, 2019). "Similarly, in neurodegenerative diseases, DHA enhances autophagy via the mTOR signaling pathway, promoting the clearance of damaged organelles and reducing neuronal toxicity." (PMID 40124417, 2025).
neurodegenerative disease (continued). "After extensive studies, mTOR could be a potential therapeutic target or biomarker for ALS and other neurodegenerative diseases that involve aggregation and misfolded proteins, among other conditions." (PMID 40299664, 2025). "Improving mitochondrial metabolism by administering succinate and/or intermittent dichloroacetic acid (DCA) as PDK (and subsequent Akt/mTOR) inhibitors, or tauroursodeoxycholic acid (TUDCA), are viewed as promising agents in ischemic brain and neurodegenerative diseases." (PMID 37629593, 2023). "Recent literatures reported that resveratrol could inhibit oxidation and apoptosis in neurodegenerative diseases through the Nrf2/HO-1, SIRT1, RAX/P-PKR, and JAK2/STAT3/PI3K/AKT/mTOR signaling pathways." (PMID 36836502, 2023). "In neurodegenerative diseases, metformin could make a positive effect by activating AMPK signaling, downregulating mTOR pathway, modulating glucose metabolism, and enhancing mitochondriogenesis and autophagy." (PMID 35769369, 2022). "Furthermore, MTOR and GSK3B are also being investigated as the potential targets for the therapeutic intervention of neurodegenerative diseases and aging." (PMID 36523604, 2022). "Regulation of AMPK/mTOR signaling to restore neuronal cell autophagy flux may represent a potential novel therapeutic approach for CORT and chronic stress‐induced neurodegenerative diseases." (PMID 31423743, 2020). "Specific activation of mTOR in RGCs or inhibition in astrocytes after injury promotes RGC regrowth and regeneration, suggesting mTOR as a potential therapeutic target for optic nerve injury and neurodegenerative disease." (PMID 31547370, 2019). "Additionally, mTOR impacts ALS and other neurodegenerative diseases." (PMID 40299664, 2025). "Hence, Akt/mTOR- and MEK/ERK-dependent signaling pathways may be potential therapeutic targets for treating neurodegenerative diseases." (PMID 33628381, 2021). "Although the Rheb–mTOR signaling pathway may act as a double-edged sword in neurodegeneration, it is a central regulator of NTFs such as BDNF, CNTF, and GDNF and thus is a potential therapeutic target for neurodegenerative diseases." (PMID 32188096, 2020). "Autophagy can be stimulated mTOR-independent mechanisms, and a number of compounds, including FDA-approved drugs, have now been shown to stimulate clearance of abnormal proteins and confer protective effects in cell or animal models of neurodegenerative disease." (PMID 28293421, 2017). "Therefore, in diabetic conditions, the dual effect of mTOR activation and AMPK inhibition synergistically suppresses autophagy initiation, impairing the clearance of damaged proteins and organelles and potentially contributing to neurodegenerative disease progression." (PMID 40660790, 2025). "Considering the importance of this pathway in a range of degenerative diseases, the data from our own preliminary studies and the lack of data on PI3K/AKT/mTOR signalling pathway in the development of MMVD, we believe investigating this pathway would be beneficial." (PMID 36869852, 2023).
metabolic disorders (190 papers, 2011 to 2026). "The mTOR pathway is known to be associated with metabolic diseases, confirming the data of our study." (PMID 38646331, 2024). "AMPK and mTOR are mutually antagonistic nutrient sensors that have been associated with several metabolic diseases, such as NAFLD." (PMID 36838721, 2023). "Beyond its well-known role in innate immunity, TBK1 has been implicated in oncogenesis and metabolic disorders linked to obesity such as type II diabetes, similar to mTOR and Akt." (PMID 34245780, 2021). "mTOR dysregulation has also been associated with the establishment of metabolic diseases, including obesity." (PMID 30986927, 2019). "Combined with the investigation of specific nsSNVs in the mTOR pathway, we infer that the southern pig-tailed macaque is probably susceptible to these metabolism disorders." (PMID 30314376, 2018). "The mechanistic target of rapamycin (mTOR) is tightly associated with several metabolic diseases and cancer." (PMID 28827765, 2017). "The mammalian target of rapamycin (mTOR) is a central metabolic regulator that has been implicated in metabolic diseases and is an important effector of metabolic signaling." (PMID 27727170, 2016). "In this sense, it has been reported that the use of PI3K/AKT/mTOR pathway inhibitors is associated with metabolic disorders and damages in skin, liver or gastrointestinal mucosa." (PMID 27765055, 2016). "At the therapeutic level, targeting inhibition of c-Fos or mTOR, or selective activation of ER, may represent new strategies for improving ovulatory function and associated metabolic disorders in PCOS." (PMID 40937413, 2025). "Metabolic disorders are also linked to abnormal immunometabolism, including mTOR hyperactivity." (PMID 39996755, 2025). "In relation to metabolic disease, mLST8 controls insulin signaling through the transcription factor FoxO3, is necessary for Akt and protein kinase C-α (PKCα) phosphorylation, and is required for Rictor to associate with mTOR." (PMID 37238686, 2023). "Ion channelopathies were the largest mechanistic group (12/31, 38.7%), followed by mitochondrial/metabolic disorders (6/31, 19.4%), mTOR pathway disorders (5/31, 16.1%), and neurodevelopmental/chromatin/transcriptional disorders (4/31, 12.9%)." (PMID 42194586, 2026). "Cross regulation between O-GlcNAcylation and mTOR signalling has also been observed in metabolic disorders." (PMID 40498175, 2025). "In disease states (such as tumors, metabolic disorders, and vascular inflammation), the imbalance between ErbB-mediated mTOR activation and the protective inhibition of AMPK becomes an important mechanism for pathological progression." (PMID 41438739, 2025). "In metabolic disorders such as diabetes and obesity, mTOR signaling is often hyperactivated, contributing to pathogenesis through mechanisms such as insulin resistance." (PMID 40804480, 2025). "Inflammasomes interact with various metabolic regulatory pathways, including the mechanistic target of rapamycin (mTOR) and peroxisome proliferator-activated receptor gamma (PPARγ), highlighting the complexity of their roles in metabolic disorders." (PMID 40433411, 2025). "Normal cell growth is maintained by a balance between the AMPK/Akt and mTOR pathways, and its deregulation can lead to metabolic disorders, resistance to apoptosis, and increased proliferation." (PMID 39596005, 2024). "The AMPK-dependent and independent regulatory roles of metformin in mTOR signaling are crucial for the overall regulation of cellular energy metabolism, and therefore for the treatment of various metabolic diseases." (PMID 38892329, 2024). "The intricate relationship between AMPK and the mTOR pathway, both of which play critical roles in regulating energy balance, holds promise as a therapeutic target for addressing metabolic disorders and carries significant clinical implications." (PMID 39409084, 2024).